KDM2A (lysine demethylase 2A)
Diseases named in the same sentence as KDM2A in open-access papers (continued):
Sharing a sentence is not in itself a finding about the gene and the disease.
atherosclerosis (2 papers, 2022 to 2025). A disease characterized by the build-up of fatty material and calcium deposition in the arterial wall resulting in partial or complete occlusion of the arterial lumen. "Given the important role of KDM2A in macrophage inflammatory response during atherosclerosis development, we investigated the association of its expression in peripheral monocytes/macrophages with coronary/carotid atherosclerotic severity." (PMID 40303308, 2025). "Diagnostic analyses validate KDM2A expression in peripheral monocytes/macrophages is an excellent predictor of atherosclerosis development and progression." (PMID 40303308, 2025). "Furthermore, the genetic association of KDM2A with atherosclerosis was validated by Mendelian randomization and colocalization analysis." (PMID 40303308, 2025). "Therefore, we believe that KDM2A expression, especially in major immune cells (T cells or macrophages), is significantly associated with atherosclerosis, suggesting that KDM2A expression is potentially linked to immune response." (PMID 40303308, 2025). "In this study, we screened KDM2A as a novel key TR playing critical roles in the development of atherosclerosis." (PMID 40303308, 2025). "In this study, we reported for the first time the detrimental role of KDM2A in the development and progression of atherosclerosis through an unbiased screening pipeline." (PMID 40303308, 2025). "A group of small molecules with the potential to target KDM2A has been identified through virtual screening, offering promising strategies for atherosclerosis treatment." (PMID 40303308, 2025). "The current study provides the novel role of KDM2A in macrophage inflammatory response of atherosclerosis through transcriptional regulation of FYN." (PMID 40303308, 2025). "And, lysine demethylase 2A (KDM2A) was identified as a key TR that specifically induces macrophage inflammatory response and atherosclerosis development through high-throughput data and in vivo experiments." (PMID 40303308, 2025). "Although we identified a novel transcriptional regulator KDM2A involved in macrophage inflammatory response and atherosclerosis, several limitations should be noted." (PMID 40303308, 2025). "After intersection analysis, three regulons (DLX2, HESX1, and KDM2A) were identified as master TRs in atherosclerosis." (PMID 40303308, 2025). "In conclusion, our finding suggests that KDM2A regulates phenotypic alterations in macrophages through the transcriptional activation of FYN during the development of atherosclerosis." (PMID 40303308, 2025). "In our study, we identified several small molecules as potential candidate for targeting KDM2A in the context of atherosclerosis." (PMID 40303308, 2025). "Therefore, we thought that our study may shed the light on the novel regulatory effect of KDM2A on atherosclerosis." (PMID 40303308, 2025). "While, we observed an obvious downregulation of pro-inflammatory markers (Il1b, Tnfa, Nos2) after Kdm2a knockdown after ox-LDL stimulation, which revealed the specific role of KDM2A in macrophages during atherosclerosis." (PMID 40303308, 2025).
colorectal adenocarcinoma (2 papers, 2022 to 2025). The most common type of colorectal carcinoma. "Consistent with our findings, miR-421 was previously highlighted as a tumor-suppressive miRNA that restrains the malignant characteristics of CRC cells, while KDM2A is known to serve as a cyclin D1-associated mediator facilitating cell proliferation and colony formation in colorectal adenocarcinoma." (PMID 35508523, 2022).
developmental delay (2 papers, 2022 to 2026). "De novo variants in KDM2A cause a syndromic neurodevelopmental disorder with a phenotypic spectrum of mild to severe developmental delay, feeding difficulties, short stature, microcephaly, and recurrent facial features." (PMID 41468891, 2026). "Using exome and genome sequencing, we identified de novo variants in KDM2A, a lysine demethylase crucial for embryonic development, in 18 individuals with developmental delays and/or intellectual disabilities." (PMID 41468891, 2026). "Developmental delay/intellectual disability and growth abnormalities are recurrent symptoms among the Mendelian disorders of the epigenetic machinery, underscoring that the KDM2A-related rare disease delineated here shows a clinical overlap." (PMID 41468891, 2026).
lymph node metastasis (2 papers, 2016 to 2021). "Clinicopathological association study demonstrated that high KDM2A is significantly correlated with large primary tumor, increased lymph node metastasis, advanced stage and high histological grade." (PMID 27029061, 2016).
multiple myeloma (2 papers, 2021). "In the present study, we demonstrated that expression of KDM2A was basically low in multiple myeloma cells." (PMID 34079757, 2021). "Our data demonstrates that in myeloma cells KDM2A interacts with PFKFB3 and mediates its ubiquitination-induced degradation." (PMID 34079757, 2021). "In the present study, we aimed to characterize the functional significance of KDM2A in multiple myeloma (MM) disease progression." (PMID 34079757, 2021). "Our findings further suggest that regulating KDM2A-mediated PFKFB3 ubiquitination may be a promising application in multiple myeloma treatment." (PMID 34079757, 2021). "This study is the first to report PFKFB3 can be ubiquitylated by KDM2A in multiple myeloma." (PMID 34079757, 2021). "Analysis of correlation between KDM2A or PFKFB3 protein levels and clinicopathological parameters of multiple myeloma patients." (PMID 34079757, 2021).
osteosarcoma (2 papers, 2018 to 2023). A usually aggressive malignant bone-forming mesenchymal neoplasm, predominantly affecting adolescents and young adults. "In human osteosarcoma cells, it has been reported that depletion of human KDM2A shortens the circadian period, while its overexpression lengthens the period." (PMID 30233643, 2018). "In addition, KDM2A/FBXL11 has been identified from a screen for F-box proteins that are required for normal circadian rhythms assayed by the expression of a clock reporter in cultured human osteosarcoma U2OS cells." (PMID 30233643, 2018). "Consistent with the screen result, targeting KDM2A using two newly designed sgRNAs (referred to as sgK#1 and sg#2) profoundly suppressed the growth of ALT-positive ALT#1, osteosarcoma Saos2, U2OS, G292, rhabdomyosarcoma Hs729, and patient-derived pGBM6 glioblastoma cells." (PMID 36991019, 2023).
psoriasis (2 papers, 2023 to 2026). An autoimmune condition characterized by red, well-delineated plaques with silvery scales that are usually on the extensor surfaces and scalp. "KDM2A is also involved in the inflammatory responses of keratinocytes in psoriasis." (PMID 41508422, 2026). "KDM2A has been confirmed to regulate the inflammatory reaction of keratinocytes in psoriasis." (PMID 37726685, 2023).
ataxia telangiectasia (1 paper, 2020). Ataxia-telangiectasia is the association of severe combined immunodeficiency (affecting mainly the humoral immune response) with progressive cerebellar ataxia. "It has been reported that ataxia telangiectasia mutated specifically phosphorylates KDM2A at threonine 632 following DNA damage, and this phosphorylation abrogates the chromatin binding activity of KDM2A." (PMID 33050392, 2020).
atrial fibrillation (1 paper, 2025). A disorder characterized by an electrocardiographic finding of a supraventricular arrhythmia characterized by the replacement of consistent P waves by rapid oscillations or fibrillatory waves that vary in size, shape and timing and are accompanied by an irregular ventricular response. "We also investigated the potential effect of KDM2A on other cardiovascular phenotypes (such as lipids, atrial fibrillation, etc.)." (PMID 40303308, 2025).
autism (1 paper, 2026). Persistent deficits in social interaction and communication and interaction as well as a markedly restricted repertoire of activity and interest as well as repetitive patterns of behavior. "Previously, two de novo missense and one de novo frameshift variant in KDM2A (MIM: 605657) were described in three individuals with autism and an NDD but only as members of much broader cohorts looking into the genetic architecture of these phenotypes." (PMID 41468891, 2026). "This prior assessment aligns with our phenotypic findings, including that both autism and epilepsy are important parts of the phenotypic spectrum of the KDM2A-related syndromic disorder, although only five affected individuals presented with seizures, and four had a diagnosis of autism." (PMID 41468891, 2026).
colon cancer (1 paper, 2017). "In the same study identifying KDM2A as demethylating p65, the authors showed that KDM2A impairs NF-κB dependent colon cancer cell growth." (PMID 28536364, 2017).
congestive heart failure (1 paper, 2025). Failure of the heart to pump a sufficient amount of blood to meet the needs of the body tissues, resulting in tissue congestion and edema. "The congestive heart failure-associated targets were Dnmt1, Hdac1, Hdac4, Ezh2, Sirt3, Kdm2a, Prkca and Prkcb (9.8% of total targets)." (PMID 40076868, 2025).
ductal carcinoma (1 paper, 2014). "Normal ducts and intact ducts in the ductal carcinoma tissue sections showed myoepithelial cells strongly positive for KDM2A, suggesting a regulatory function of KDM2A in these cells." (PMID 25029110, 2014).
female subfertility (1 paper, 2022). "Knockout of Kdm2a possibly increased H3K36me2/3 levels and disturbed the expression of genes required for chromatin condensation and oogenesis and maturation, which blocked oocyte meiotic maturation and caused female subfertility." (PMID 36233308, 2022).
infiltrating ductal carcinoma (1 paper, 2014). "Ductal cells from ductal carcinoma in situ (DCIS) and infiltrating ductal carcinoma (IDC) show positive staining for KDM2A, the expression decreases with disease progression to metastasis." (PMID 25029110, 2014).
intestinal cancer (1 paper, 2017). "The strongest effect was observed for the K793N mutant found in intestinal cancer which showed ∼50% reduced HP1 binding compared to WT KDM2A." (PMID 28180290, 2017).
leukemia (1 paper, 2023). A malignant (clonal) hematologic disorder, involving hematopoietic stem cells and characterized by the presence of primitive or atypical myeloid or lymphoid cells in the bone marrow and the blood. "The histone lysine demethylase KDM2A was described to be an opposing regulator of ASH1L by specifically demethylating H3K36me2, which leads to the dissociation of KMT2A/PS1P1 and the decreased description of KMT2A target leukemia genes." (PMID 37296904, 2023).
liver cancer (1 paper, 2023). An epithelial or non-epithelial malignant neoplasm that arises from the liver. "It is worth noting that the putative ZHX2-binding motif is also located in the previously reported ZHX2 target genes, such as Cyclin E and KDM2A, which are involved in liver cancer progression." (PMID 37980429, 2023).
liver diseases (1 paper, 2023). "Further studies will be required to assess the role of KDM2A in recruiting other types of immune cells in a cytokine-dependent manner in various liver diseases." (PMID 37892137, 2023).
lymphoma (1 paper, 2021). A malignant (clonal) proliferation of B- lymphocytes or T- lymphocytes which involves the lymph nodes, bone marrow and/or extranodal sites. "Inside the KDM2A gene, 112 translocations were detected in lymphoma cells but only 35 in T cells." (PMID 34359791, 2021).
melanoma (1 paper, 2017). A malignant, usually aggressive tumor composed of atypical, neoplastic melanocytes. "Our results provide insights into the in vivo function of KDM2A throughout the complete life span of a vertebrate model organism and establish kdm2aa-deficient zebrafish as a new model to study the aetiology of triple wild-type melanoma." (PMID 28806732, 2017). "KDM2A is not among the commonly mutated chromatin modifiers in melanoma, but code-disrupting mutations have been identified in melanomas and other cancers." (PMID 28806732, 2017).
metabolic syndrome (1 paper, 2023). A cluster of metabolic risk factors for CARDIOVASCULAR DISEASES and TYPE 2 DIABETES MELLITUS. "Given our findings, it is reasonable to speculate that Kdm2a liver deficiency may contribute to the incidence of high metabolic syndrome in NAFLD patients." (PMID 37892137, 2023).
myeloid leukemia (1 paper, 2021). A clonal proliferation of myeloid cells and their precursors in the bone marrow, peripheral blood, and spleen. "KDM2A activity thus counteracts MLL-driven leukemogenesis, underlining an anti-leukemic role for KDM2A in myeloid leukemias." (PMID 34944554, 2021).
myocardial infarction (1 paper, 2021). Gross necrosis of the myocardium, as a result of interruption of the blood supply to the area, as in coronary thrombosis. "High expression of miR-134-5p promotes myocardial apoptosis and angiogenesis after myocardial infarction by targeting XIAP and KDM2A." (PMID 34233591, 2021).
oral cancer (1 paper, 2022). "Therefore, KDM2A may be a new therapeutic target for oral cancer treatment." (PMID 34117688, 2022).
pancreatic tumors (1 paper, 2025). "KDM2A acts as an epigenetic regulator of mTORC1 signaling, and KDM2A-deficient pancreatic tumors show increased sensitivity to mTORC1 inhibition." (PMID 40619414, 2025).
polymicrogyria (1 paper, 2026). A developmental brain abnormality characterized by an excessive amount of small convolutions on the surface of the brain and cognitive dysfunction. "It remains, therefore, unclear whether polymicrogyria is part of the phenotypic spectrum of the KDM2A-related disorder or if another, undetected genetic cause is involved." (PMID 41468891, 2026).
renal carcinoma (1 paper, 2024). A carcinoma arising from the epithelium of the renal parenchyma or the renal pelvis. "NUF2 acts as an oncogene in renal cancer by affecting the expression of HMGA2 by KDM2A-mediated H3K36me2 demethylation." (PMID 39242581, 2024).
rhabdoid tumor (1 paper, 2024). An aggressive malignant embryonal neoplasm usually occurring during childhood. "On a brighter note, inhibition of the H3K36 demethylase KDM2A was recently demonstrated to rescue resistance to EZH2 inhibition conferred by loss of the H3K36 methyltransferase NSD1 in SMARCB1-deficient rhabdoid tumor cell lines." (PMID 39403928, 2024).
schizophrenia (1 paper, 2024). A major psychotic disorder characterized by abnormalities in the perception or expression of reality. "A dozen missense, silent, intronic, and frameshift variants in KDM2A have been documented in individuals diagnosed with ASD, and schizophrenia." (PMID 39519104, 2024).
Testicular atrophy (1 paper, 2025). Wasting (atrophy) of the testicle (the male gonad) manifested by a decrease in size and potentially by a loss of fertility. "Loss of Kdm2a in sKO resulted in severe testicular atrophy at 26 d of age, with a 72% decrease in testes to body weight ratio compared to Kdm2a2lox/+; Ngn3-Cre Ctrl." (PMID 40701999, 2025).
cancer (48 papers, 2014 to 2025). A tumor composed of atypical neoplastic, often pleomorphic cells that invade other tissues. "Our previous study found that cancer-secreted IL-6 can upregulate the expression of KDM2A to promote further the transition of cells into cancer-associated fibroblasts (CAFs)." (PMID 37821959, 2023). "Both KDM2A and canonical Wnt signaling play important roles in stem cells, and their misregulation is associated with various cancers." (PMID 37998355, 2023). "The dysfunction of KDM2A has been reported in various cancers, and its loss-of-function mouse mutants are embryonically lethal." (PMID 34391411, 2021). "Evolutionary conservation and an enrichment of cancer-associated single nucleotide variations that potentially interfere with the KDM2A/HP1 interaction indicate an important biological function for the HP1 binding motif." (PMID 28180290, 2017). "Additionally, cancer-derived interleukin-6 (IL-6) activates KDM2A in cancer-associated fibroblasts via the STAT3/NF-κB p50 pathway, promoting stromal-mediated resistance." (PMID 40941035, 2025). "In the future, it will be important to investigate which TCF/LEF regions and, more specifically, which amino acid residues are responsible for the KDM2A-mediated destabilization and whether these amino acid residues are mutated in certain types of cancer." (PMID 37998355, 2023). "Moreover, KDM2A is closely linked to the metastasis and progression of several cancers, including lung cancer, gastric cancer, cervical cancer, and glioblastoma." (PMID 37821959, 2023). "There is increasing evidence that KDM2A is involved in cancer formation but the underlying molecular mechanisms remain unclear." (PMID 28180290, 2017). "Chen et al110 recently reported that lysine-specific demethylase 2A (KDM2A) expression can be stimulated in normal fibroblasts by cancer-derived cytokines, including IL-6; this results in the transformation of these fibroblasts into cancer-associated fibroblasts (CAFs)." (PMID 40584290, 2025). "KDM2A suppresses histone deacetylase 3 in non–small-cell lung cancer cells, enhancing cancer cell proliferation and invasiveness by demethylating of H3K36me2 at histone deacetylase 3 promoter region." (PMID 39938867, 2025). "KDM2A enhances cancer stem cell traits and angiogenesis through JAG1 activation and represses tumor suppressors such as E-cadherin by inhibiting TET2." (PMID 40941035, 2025). "While some reports suggest that KDM2A affects cancer cell proliferation positively, KDM2A was also shown to affect cell proliferation negatively." (PMID 40427554, 2025). "Specifically, modifiers like KDM2A have an oncogenic effect on many cancers, whereas others such as SETD2 and KMT2D play tumor suppressive roles." (PMID 39765675, 2024). "Results from this study thus support efforts to develop KDM2A inhibitors targeting ALT-dependent cancers." (PMID 36991019, 2023). "Here, the authors identify KDM2A as a molecular vulnerability in ALT-dependent cancer cells and demonstrate its role in the resolution of ALT-specific telomere clusters via recruitment of SENP6." (PMID 36991019, 2023). "For example, abnormally high levels of KDM2A promote tumor cell growth in breast cancer, lung cancer, and gastric cancer, whereas canonical Wnt signaling is aberrantly active in cancer stem cells." (PMID 37998355, 2023). "This study identifies KDM2A as a promising therapeutic target that is selective for ALT-dependent cancers." (PMID 36991019, 2023). "Lysine Demethylase 2A (KDM2A) plays a crucial role in cancer cell growth, differentiation, metastasis, and the maintenance of cancer stemness." (PMID 37821959, 2023). "As replication stress-induced DNA damage and repair are common features of human cancers, it will be interesting in the future to evaluate the molecular functions of KDM2A and, more broadly, H3K36 methylation and demethylation in those processes." (PMID 36991019, 2023).